CETN2 (centrin 2)
Description:
Plays a fundamental role in microtubule organizing center structure and function. Required for centriole duplication and correct spindle formation. Has a role in regulating cytokinesis and genome stability via cooperation with CALM1 and CCP110. Involved in global genome nucleotide excision repair (GG-NER) by acting as component of the XPC complex. Cooperatively with RAD23B appears to stabilize XPC. In vitro, stimulates DNA binding of the XPC:RAD23B dimer. The XPC complex is proposed to represent the first factor bound at the sites of DNA damage and together with other core recognition factors, XPA, RPA and the TFIIH complex, is part of the pre-incision (or initial recognition) complex. The XPC complex recognizes a wide spectrum of damaged DNA characterized by distortions of the DNA helix such as single-stranded loops, mismatched bubbles or single-stranded overhangs. The orientation of XPC complex binding appears to be crucial for inducing a productive NER. XPC complex is proposed to recognize and to interact with unpaired bases on the undamaged DNA strand which is followed by recruitment of the TFIIH complex and subsequent scanning for lesions in the opposite strand in a 5'-to-3' direction by the NER machinery. Cyclobutane pyrimidine dimers (CPDs) which are formed upon UV-induced DNA damage esacpe detection by the XPC complex due to a low degree of structural perurbation. Instead they are detected by the UV-DDB complex which in turn recruits and cooperates with the XPC complex in the respective DNA repair. As a component of the TREX-2 complex, involved in the export of mRNAs to the cytoplasm through the nuclear pores.
Synonyms: CALT; CEN2
Tractability: Small molecule: a structure with a bound ligand is known; it has a binding pocket of medium quality. PROTAC: UniProt records ubiquitination sites on it; ubiquitination databases record sites on it; its protein half-life has been measured.
Gene: Protein-coding gene on chromosome X (152,826,994 to 152,830,782, reverse strand). Ensembl gene ENSG00000147400.
Subcellular location: Cytoplasm, cytoskeleton, microtubule organizing center, centrosome; Cytoplasm, cytoskeleton, microtubule organizing center, centrosome, centriole; Nucleus envelope; Nucleus, nuclear pore complex; Nucleus
Subcellular location (Human Protein Atlas): Flagellar centriole; Nucleoplasm; Centrosome; Mid piece; Principal piece
Pathways (Reactome):
Cell Cycle: AURKA Activation by TPX2; Loss of Nlp from mitotic centrosomes; Loss of proteins required for interphase microtubule organization from the centrosome; Recruitment of NuMA to mitotic centrosomes; Recruitment of mitotic centrosome proteins and complexes; Regulation of PLK1 Activity at G2/M Transition
DNA Repair: DNA Damage Recognition in GG-NER; Formation of Incision Complex in GG-NER
Metabolism of proteins: SUMOylation of DNA damage response and repair proteins
Organelle biogenesis and maintenance: Anchoring of the basal body to the plasma membrane
Gene Ontology:
Molecular function: protein binding; calcium ion binding; G-protein beta/gamma-subunit complex binding; heterotrimeric G-protein binding; microtubule binding
Biological process: centriole replication; nucleotide-excision repair; regulation of cytokinesis; microtubule cytoskeleton organization; mitotic cell cycle; mRNA export from nucleus; positive regulation of transcription by RNA polymerase II; spermatogenesis
Cellular component: centriole; centrosome; nuclear envelope; nuclear pore nuclear basket; nucleoplasm; sperm midpiece; sperm principal piece; transcription export complex 2; XPC complex; cytosol; nucleus; 9+2 motile cilium; apical part of cell; ciliary basal body; cilium; nuclear pore; photoreceptor connecting cilium
Homologues: Orthologues: chimpanzee CETN2 (100% identical), chimpanzee CETN2 (99% identical), macaque CETN2 (99% identical), dog CETN2 (98% identical), rabbit CETN2 (97% identical), rat Cetn2 (97% identical), pig CETN2 (97% identical), mouse Cetn2 (96% identical), Caenorhabditis elegans cal-1 (36% identical), Caenorhabditis elegans cal-3 (36% identical), Caenorhabditis elegans B0563.7 (33% identical), Caenorhabditis elegans E02A10.3 (33% identical), and 11 more. Paralogues in human: CETN1 (83% identical), CETN3 (53% identical), CALM1 (44% identical), CALM2 (44% identical), CALM3 (44% identical), CALML3 (41% identical), CABP2 (34% identical), CABP4 (33% identical), CALML5 (32% identical), CABP1 (31% identical), CABP5 (31% identical), CALML6 (31% identical), and 8 more.
Diseases named in the same sentence as CETN2 in open-access papers:
CETN2 is named in the same sentence as 30 diseases in open-access papers, as found by Europe PMC text mining. Sharing a sentence is not in itself a finding about the gene and the disease. The quoted sentences say what the papers report.
xeroderma pigmentosum group C (5 papers, 2012 to 2021). An autosomal recessive inherited disorder caused by mutations in the XPC gene. "First, Cetn2 is an integral component of the nucleotide excision repair/xeroderma pigmentosum group C (XPC–RAD23–CETN2) complex." (PMID 28560031, 2017). "In GG-NER, recognition of DNA damage is primarily through a complex of xeroderma pigmentosum, complementation group C (XPC) protein, UV excision repair protein Radiation sensitive 23B (RAD23B) protein and Centrin 2 (CETN2), which detects single-stranded DNA." (PMID 34884434, 2021). "In combination with biochemical reconstitution assays, this method demonstrated that locating bulky lesions depends on a heterotrimeric factor composed of xeroderma pigmentosum group C (XPC;) one of two human RAD23 homologs (predominantly RAD23B;) and centrin 2 (CETN2;)." (PMID 26521083, 2016).
bladder cancer (2 papers, 2020). "Down-regulation of CETN2 was reported to be involved in tumor suppressive functions in bladder cancer." (PMID 32101536, 2020). "It was reported that the down-regulated of CETN2 might have tumor suppressive function in bladder cancer." (PMID 32874133, 2020).
asthma (1 paper, 2020). "Therefore, LRRC48 and CETN2 can be considered as candidate predictive biomarkers for the asthma-COPD." (PMID 31952466, 2020). "Among ten hub DEGs identified for the asthma-COPD, nine DEGs including SPAG6, C7orf57, SYTL3, LRRC48, TEKT3, CCDC146, CETN2, CCDC19, and C14orf45 were identified as the novel genes." (PMID 31952466, 2020). "In addition, other identified genes were LRRC48 and CETN2 in asthma-COPD, COL15A1, GIMAP6, and JAM2 in asthma-IPF, along with LMO7, TSPAN13, LAMA3, and ANXA3 in COPD-IPF." (PMID 31952466, 2020). "These genes included RBM42, STX5, and TRIM41 in asthma, CYP27A1, GM2A, LGALS9, SPI1, and NLRC4 in COPD, ATF3, PPP1R15A, ZFP36, SOCS3, NAMPT, and GADD45B in IPF, LRRC48 and CETN2 in asthma-COPD, COL15A1, GIMAP6, and JAM2 in asthma-IPF and LMO7, TSPAN13, LAMA3, and ANXA3 in COPD-IPF." (PMID 31952466, 2020).
astrocytomas (1 paper, 2022). "Among these, CETN2 mRNA has been described to be overexpressed in astrocytomas and in its most aggressive form, GBM." (PMID 35573835, 2022).
brain tumors (1 paper, 2022). "Collectively, these findings support the validity of CETN2 as a novel marker of brain tumors." (PMID 35573835, 2022).
chlamydia infection (1 paper, 2023). "Our work highlights the importance of CETN2 in the regulation of centrosome amplification in chlamydia infection." (PMID 37155906, 2023).
chlamydial infection (1 paper, 2023). "Our data indicate that CteG, through interactions with CETN2, contributes to induction of centrosome amplification during chlamydial infection." (PMID 37155906, 2023). "Our data indicate that CteG plays a role in centrosome amplification during chlamydial infection, which we hypothesize is due to its interaction with CETN2." (PMID 37155906, 2023).
colon cancer (1 paper, 2025). "Collectively, our findings provide compelling evidence for the involvement of the GPER1-PKA-Centrin-2 axis in regulating centrosome numbers and centriole integrity in a colon cancer-derived in vitro model." (PMID 41299155, 2025). "This suggests that phosphorylation of Centrin-2 at serine 170 may contribute to the regulation of both the numerical and structural centriole integrity prior to mitosis in an in vitro colon cancer model under conditions of experimentally enhanced GPER-PKA activity." (PMID 41299155, 2025).
glioblastoma multiforme (1 paper, 2022). "Our results demonstrate that CETN2 is expressed in astrocytes of primary glioblastomas, in a stage of tumor progression which is, by definition, the most severe." (PMID 35573835, 2022). "As a prototypical condition with glial overproliferation, we also explored CETN2 expression in glioblastoma multiforme (GBM), reporting a focal concentration of CETN2 in neoplastic astrocytes." (PMID 35573835, 2022).
myeloma (1 paper, 2013). "Expression of some genes connected with centrosome formation and function (AURKA, AURKB, CETN2, and PLK4) was significantly different between hyperdiploid and non-hyperdiploid myeloma patients." (PMID 23522059, 2013).
osteosarcoma (1 paper, 2013). A usually aggressive malignant bone-forming mesenchymal neoplasm, predominantly affecting adolescents and young adults. "We have previously found that CDC25B overexpression in the human osteosarcoma cell line U2OS, causes centrosome amplification and that CDC25B associates with centrin 2, an integral component of both mature and assembling centrioles." (PMID 23840880, 2013).
ovarian carcinoma (1 paper, 2020). A malignant neoplasm originating from the surface ovarian epithelium. "Thus, network-based INCM analysis generates a hypothesis for a potential synthetic lethal interaction for CETN2 and CDK4 co-mutated ovarian cancer." (PMID 32101536, 2020).
retinal degeneration (1 paper, 2025). Degeneration of the retina. "It is worth noting that disruptions in Cetn2 expression solely do not have extensive implications for retinal degeneration due to Cetn3 redundancy." (PMID 40558514, 2025).
cancer (7 papers, 2013 to 2025). A tumor composed of atypical neoplastic, often pleomorphic cells that invade other tissues. "Given the role of calcium signaling in GBM infiltration, a role of CETN2 in determining the susceptibility of specific regions to cancer growth cannot be excluded." (PMID 35573835, 2022). "In addition, CETN2 was also involved in nucleotide excision repair that was linked with the risk of cancer." (PMID 32874133, 2020). "We report that overexpression of CDC25B, as is commonly found in human cancer, results in a significant increase in centrin 2 at the centrosomes of interphase cells." (PMID 23840880, 2013). "CETN2 is a ubiquitous protein component present in the centrosome and polar body of the mitotic spindle, and abnormalities in centrosome replication are prevalent in various cancers, which are already occasionally present in precancerous lesions." (PMID 37251926, 2023). "Only a few studies have revealed a link between CETN2 and cancer." (PMID 35205612, 2022). "Accumulating evidences demonstrated that CETN2 was identified in various types of cancers." (PMID 32874133, 2020). "In addition, the presence of CETN2-positive cells in vessels within cancer may reinforce our speculation over CETN2 in affecting blood flow, a parameter that may be relevant to tumor growth." (PMID 35573835, 2022). "Cancer cells were treated with YLT-11, then centrioles and centrosomes were determined by immunostaining for centrin 2 and γ-tublin, respectively." (PMID 30337519, 2018). "However, the mechanism of CETN2 action in cancers, specifically HCC, was not identified." (PMID 35205612, 2022).
tumor (7 papers, 2018 to 2023). "Based on these considerations, we also explored CETN2 expression in GBM as a prototypical tumor with glial overgrowth." (PMID 35573835, 2022). "In this module, Ercc3 and Cetn2 (centrin 2) were positively correlated with tumor size." (PMID 30327455, 2018). "However, the question of whether in neoplastic astrocytes CETN2 triggers tumor initiation, a function that is mostly related to its involvement in DNA repair, or tumor growth, by affecting intracellular calcium signaling or angiogenesis will be subject of future investigations." (PMID 35573835, 2022). "In terms of clinicopathological correlation, CETN2, MPZL1, RACGAP1, and SNRPB were upregulated in patients with microvascular invasion, and the expression of MPZL1 and SNRPB was increased in proportion to the Edmonson tumor differentiation grade." (PMID 35205612, 2022).
infection (2 papers, 2020 to 2023). The state of being infected such as from the introduction of a foreign agent such as serum, vaccine, antigenic substance or organism. "Our results implicate both CteG and CETN2 in infection-associated centrosome amplification." (PMID 37155906, 2023). "Our data indicate that both CteG and CETN2 are necessary for infection-induced centrosome amplification, in a manner that requires the C-terminus of CteG." (PMID 37155906, 2023). "Interestingly, other NER genes involved in damage recognition, such as DDB1, CETN2, and RBX1, were found to be downregulated during the infection and, in the case of DDB1, data support a putative involvement of CagA." (PMID 33339161, 2020).
adenocarcinoma (1 paper, 2013). A common cancer characterized by the presence of malignant glandular cells. "Similar centrin “foci” or “satellites” have been observed previously, in G1/S-arrested Chinese Hamster Ovary (CHO) cells, in HeLa cells overexpressing a phosph-mimetic form of centrin 2 and in A549 human adenocarcinoma cells following DNA damage." (PMID 23840880, 2013).
CETN2 also shares sentences with these, for which no sentence is quoted: Cirrhosis (3 papers); breast carcinoma (2); bile duct cancer (1); Cockayne syndrome (1); dementia (1); esophageal cancer (1); esophageal squamous cell carcinoma (1); Hydrocephalus (1); intrahepatic bile duct cancer (1); invasive ductal carcinoma of the breast (1); kidney stones (1); liver fibrosis (1); lymphoma (1).